EPAS1 (endothelial PAS domain protein 1)
Diseases named in the same sentence as EPAS1 in open-access papers (continued):
Sharing a sentence is not in itself a finding about the gene and the disease.
pheochromocytoma (continued). "Similarly, phaeochromocytoma showed a significantly lower proportion of EPAS1 DNA deletion when compared to paragangliomas (15.97% versus 42.86%)." (PMID 33114456, 2020). "In brief, phaeochromocytomas had higher EPAS1 mRNA expressions when compared with paragangliomas." (PMID 33114456, 2020). "In addition, EPAS1 DNA number changes (ratio of expression) in phaeochromocytomas/paragangliomas were significantly (p < 0.01) higher when compared to that of non-neoplastic adrenal tissues (1.486 ± 0.011 versus 1.186 ± 0.015)." (PMID 33114456, 2020). "These mutations were noted to be related with altered expression and/or structural and functional changes in EPAS1, which in turn could play an important role in the pathogenesis of phaeochromocytomas and paragangliomas." (PMID 33114456, 2020). "The differential EPAS1 DNA number and mRNA expression in phaeochromocytomas and paragangliomas implied that the aberration of EPAS1 could affect these tumours in a different manner." (PMID 33114456, 2020). "In addition, EPAS1 DNA number variation, mRNA, protein expressions and their correlation with clinical and pathological features of patients with phaeochromocytomas and paragangliomas were also investigated." (PMID 33114456, 2020). "This served as genetic confirmation of isolated EPAS1-gain-of-function syndrome and allowed the evaluation of HIF-2α in the absence of common somatic mutations causing alterations in the hypoxia pathway resulting in paraganglioma/pheochromocytoma." (PMID 31185588, 2019). "A pseudohypoxic transcriptional signature characterizes pheochromocytomas and paragangliomas (PPGLs) of the cluster I, mainly represented by tumors with mutations in von Hippel–Lindau (VHL), endothelial PAS domain-containing protein 1 (EPAS1), or succinate dehydrogenase (SDH) subunit genes." (PMID 31142060, 2019). "All three groups (EPAS1/HIF2α vs. cluster 1 vs. cluster 2) showed a similar TH expression independent of HIF2α expression, which is in accordance with our in vitro findings using mouse pheochromocytoma cells expressing Hif2α." (PMID 31035382, 2019). "Thus, the molecular dysregulation of EPAS1 could play crucial roles in the pathogenesis of phaeochromocytomas and paragangliomas." (PMID 33114456, 2020). "Importantly, the association of EPAS1 DNA number amplification (p = 0.037) and EPAS1 mRNA expression (p = 0.001) with tumour location (adrenal gland versus carotid body) suggested the clinical significance of EPAS1 in the carcinogenesis of phaeochromocytomas and paragangliomas." (PMID 33114456, 2020). "The mutation analysis of EPAS1 in 71 phaeochromocytomas and paragangliomas resulted in the identification of two heterozygous somatic mutations, which have not been previously reported in phaeochromocytomas and paragangliomas." (PMID 33114456, 2020). "The immunofluorescence staining of EPAS1 in the representative phaeochromocytomas/paragangliomas and non-neoplastic adrenal tissue samples showed a different degree of staining under confocal microscopy." (PMID 33114456, 2020). "However, the molecular dysregulation and clinical significance of EPAS1 has never been investigated in depth in phaeochromocytomas/paragangliomas." (PMID 33114456, 2020).
iron deficiency (48 papers, 2009 to 2026). "In contrast, an iron responsive element (IRE) is found in the 5′untranslated region of the EPAS1 sequence, and the translation of the HIF-2α protein can be repressed by the binding of iron regulatory proteins to the 5′IRE of EPAS1 during iron deficiency." (PMID 36923253, 2023). "During iron deficiency in mammals, hypoxia-inducible factor 2α (HIF-2α, also known as EPAS1) activates the transcription of DMT1, FPN1 and DCYTB genes in the intestine to increase iron absorption." (PMID 24904417, 2014). "Like mammals, intestinal iron absorption in C. elegans is upregulated during iron deficiency by HIF-transcriptional activation of smf-3/DMT1 (C. elegans, HIF-1; human, HIF-2α, EPAS1)." (PMID 31532389, 2019).
paraganglioma (47 papers, 2013 to 2026). A benign or malignant neoplasm arising from paraganglia located along the sympathetic or parasympathetic nerves. "Pacak–Zhuang syndrome is a syndrome resulting from somatic gain-of-function mutations in HIF2α encoded by the EPAS1 gene, which occurs early in embryogenesis, and paraganglioma is one of the characteristics of Pacak–Zhang syndrome." (PMID 38339335, 2024). "Contrastingly, in paragangliomas, 7% (n = 1/14) of patients had EPAS1 mutations and only the c.1091A>T; p.Lys364Met mutation was detected." (PMID 33114456, 2020). "At the same time, EPAS1 mutation, an activating mutation, could decrease the degradation of HIF2α and result in Pacak–Zhuang syndrome, which could result in paraganglioma." (PMID 38339335, 2024). "In paragangliomas, 7% (1/14) of patients had shown EPAS1 mutations." (PMID 33114456, 2020).
colorectal cancer (45 papers, 2008 to 2025). A primary or metastatic malignant neoplasm that affects the colon or rectum. "EPAS1 rs34533650 significantly increased colorectal cancer risk in the Chinese population, and this result was validated in the Japanese and European populations." (PMID 37994607, 2024). "EPAS1 expression level was associated with the vast majority of T cell markers in colorectal cancer data." (PMID 37994607, 2024). "Association analyses between rs34533650 in EPAS1 and colorectal cancer risk in discovery and validation stages." (PMID 37994607, 2024). "In the Chinese population, compared with the most common haplotype AC, the haplotype GC in the EPAS1 gene significantly increased colorectal cancer risk." (PMID 37994607, 2024). "EPAS1 expression was associated with the vast majority of immune markers for different types of immune cells in colorectal cancer." (PMID 37994607, 2024). "In summary, our research showed that the genetic variant rs34533650 A > G in EPAS1 was associated with colorectal cancer risk." (PMID 37994607, 2024). "EPAS1 expression leads to increased tumor growth and metastasis and is significantly associated with the occurrence, development, and prognosis of colorectal cancer." (PMID 36324584, 2022). "For example, in colorectal carcinoma, EPAS1 protein expression inversely correlated with higher tumor grade and plasma mRNA level of EPAS1 expression and is associated with poor patients' survival and advanced pathological stages." (PMID 33042797, 2020). "Among the ten transcription regulators, we noted that the overexpression of EPAS1 was associated with poor prognosis in colorectal carcinoma, according to previous reports." (PMID 29228695, 2017). "Another example is transcriptional factor, responsible for the activation of VEGF and angiogenesis, EPAS1 (hypoxia inducible factor 2a, changed in 8.2% of cases), that is once expressed in stroma is associated with a poorer prognosis in colorectal cancer." (PMID 24416320, 2014). "Association analyses between rs34533650 in EPAS1 and colorectal cancer risk in Chinese populations." (PMID 37994607, 2024). "In colorectal cancer, 16% (n = 13/82) patients had shown EPAS1 mutations in the present study." (PMID 34250767, 2021). "EPAS1 might be a potential independent biomarker for colorectal cancer risk and immune regulation." (PMID 37994607, 2024). "Similarly, EPAS1 expression was significantly decreased in colorectal tumour tissues and highly malignant tissues, indicating that EPAS1 may play an inhibitory role in colorectal cancer risk." (PMID 37994607, 2024). "SNP rs34533650 influences EPAS1 expression in an allele‐specific manner, and EPAS1 expression was associated with the infiltration levels of macrophages, suggesting that genetic variants may influence immune infiltration through the expression of EPAS1 gene associated with colorectal cancer risk." (PMID 37994607, 2024). "In colorectal cancer, EPAS1 expression was significantly correlated with the expression of well‐known T cell checkpoints including PD‐1, PD‐L1 and CTLA‐4." (PMID 37994607, 2024). "The EPAS1 expression was positively correlated with the expression of immune checkpoints for T cells in colorectal cancer." (PMID 37994607, 2024). "EPAS1 is downregulated at the mRNA level in cancerous tissues, and the same trend was found in colorectal cancer." (PMID 37994607, 2024). "The HIF pathway, including HIF‐1α, EPAS1, HIF‐3α and ARNT, is associated with disease progression and adverse clinical outcomes in colorectal cancer." (PMID 37994607, 2024). "Through GSEA, intestinal immune‐associated pathway and cancer‐related pathway were enriched based on EPAS1 expression in colorectal cancer." (PMID 37994607, 2024). "EPAS1 expression and immune marker genes were significantly correlated in immune infiltrating cells in colorectal cancer." (PMID 37994607, 2024).
colorectal cancer (continued). "In colorectal carcinoma, the EPAS1 protein expression inversely correlated with higher tumor grade and is associated with poor prognosis." (PMID 34917133, 2021). "In colorectal carcinoma (CRC), the expression of EPAS1 has been associated with the pathological stages, histological grade, size, recurrence and survival of the patients." (PMID 34250767, 2021). "In addition, we found that EPAS1 copy number variation (CNV) was associated with the degree of infiltration of immune cells and observed correlations between EPAS1 expression and immune cell infiltration levels in colorectal cancer." (PMID 37994607, 2024). "In colorectal cancer, EPAS1 expression was negatively correlated with tumor grades, and mRNA expression of EPAS1 was significantly lower in primary colorectal cancer tissues than in healthy tissues and correlated with advanced pathological stages III and IV and poor patient survival." (PMID 36324584, 2022). "For instance, lncRNA HIF2PUT acts as a direct upstream promoter inducing EPAS1 (HIF2A) expression in colorectal cancer and consequently increasing angiogenesis; another example is the lncRNA PVT1, which stabilizes STAT3 and therefore indirectly increases VEGF expression in gastric cancer." (PMID 33333852, 2020). "However, the molecular behaviours, functional roles and mutational status of EPAS1 have never been studied in colorectal carcinoma (CRC)." (PMID 34250767, 2021). "To investigate how EPAS1 affects colorectal cancer, we observed positive correlations between EPAS1 and angiogenesis, quiescence, differentiation, EMT, metastasis and hypoxia in colorectal cancer at the single‐cell level." (PMID 37994607, 2024).
melanoma (39 papers, 2007 to 2025). A malignant, usually aggressive tumor composed of atypical, neoplastic melanocytes. "The results revealed that melanoma cells exhibited substantial expression of critical stemness-associated genes, namely HIF1A, EPAS1, TWIST1 and EZH2." (PMID 41383633, 2025). "Using an ACT model against melanoma in female mice, this study revealed the impact of aging and modulation of Epas1 expression on anti-tumor responses of CD8 T cells." (PMID 39925817, 2025). "Amongst these, ABCB1, DNMT3B, EPAS1, JARID1B and TERT have previously been designated as melanoma CSC(-associated) markers (and reviewed in 13)." (PMID 24098529, 2013). "In accordance, EPAS1/HIF2A, a hypoxia-inducible factor that enables cancer cells to adapt to low oxygen conditions, was found upregulated in the melanoma SP." (PMID 24098529, 2013). "Interestingly, high expression of EPAS1 has been observed in melanoma with poor prognosis." (PMID 24098529, 2013). "In further support, the melanoma SP shows upregulated expression of factors that by others have been assigned to (candidate) melanoma CSC, including ABCB1, DNMT3B, EPAS1, JARID1B and TERT." (PMID 24098529, 2013).
osteoarthritis (39 papers, 2007 to 2026). A noninflammatory degenerative joint disease occurring chiefly in older persons, characterized by degeneration of the articular cartilage, hypertrophy of bone at the margins and changes in the synovial membrane. "Research indicates that EPAS1 induces ferroptosis in clear cell carcinoma by upregulating hypoxia-induced lipid droplet-associated expression and that D-mannose modulates ferroptosis via EPAS1 to alleviate osteoarthritis progression." (PMID 40165005, 2025). "Previously, we demonstrated that HIF-2α (encoded by Epas1), a transcription factor regulated by oxygen tension, acts as an essential catabolic regulator of osteoarthritis (OA) by modulating the expression of various catabolic factors, including MMPs, in chondrocytes." (PMID 26510617, 2015). "Endothelial Per-Arnt-Sim domain protein-1/hypoxia-inducible factor-2α (EPAS-1/ HIF-2α) is a catabolic transcription factor that regulates osteoarthritis (OA)-related cartilage destruction." (PMID 29263346, 2017). "D‐mannose alleviates osteoarthritis progression via EPAS1 through ferroptosis." (PMID 38722283, 2024).
pancreatic cancer (36 papers, 2012 to 2026). "Another hypoxia-associated major transcription factor, HIF2α (also called endothelial PAS domain protein 1 [EPAS1]) in pancreatic cancer, was targeted using NPs with siRNA loaded onto a polyethylenimine-poly(lactide-coglycolide) (PLGA)/poloxamer." (PMID 35057033, 2022). "For example, siRNA mediated silencing of EPAS1 induced reduce proliferation of cells, higher number of apoptosis and produced smaller tumour in pancreatic carcinoma xenotransplanted mouse model." (PMID 34250767, 2021).
kidney cancer (34 papers, 2011 to 2026). Primary or metastatic malignant neoplasm involving the kidney. "Given DoRothEA is not tissue specific, we sought to confirm that the HIF TFs bind to the target genes in ccRCC by using ChIP-seq data from HIF1A and EPAS1 (also known as HIF2A) in kidney cancer cell lines (see “Methods”)." (PMID 39633487, 2024).
Obesity (30 papers, 2011 to 2026). Accumulation of substantial excess body fat. "A pivotal finding from our research highlights the loss of EPAS1-regulated homeostasis during obesity, a global epidemic and major contributor to cardiovascular disease." (PMID 39234692, 2024). "To confirm the influence of obesity on endothelial EPAS1 levels, we analyzed an alternative model of obesity using mice with homozygous deficiency in leptin (Lepob/ob), which gained weight more rapidly than littermate controls." (PMID 39234692, 2024). "Therefore, obesity induced through either exposure to a HFD or genetic loss of leptin led to a substantial reduction in EPAS1 levels in aortic endothelium." (PMID 39234692, 2024). "We investigated whether reduced serum EPAS1 in clinical obesity was associated with altered circulating lipids and ROS." (PMID 39234692, 2024). "Thus, HFD feeding associated with obesity reduces EPAS1 expression at a LOSS atheroprone region." (PMID 39234692, 2024). "Our study concludes that obesity leads to the suppression of EPAS1 in arterial EC, unveiling a novel molecular mechanism contributing to obesity-driven atherosclerosis." (PMID 39234692, 2024). "Our subsequent experiments delineated the mechanism for EPAS1 regulation in obesity, focusing on the potential effects of hyperlipidemic and hyperglycemic metabolic disturbances." (PMID 39234692, 2024). "To assess the effect of obesity on aortic endothelial EPAS1 levels, we exposed WT mice to HFD or a normal chow diet for 22 weeks." (PMID 39234692, 2024). "Overall, obesity in mice led to reduced EPAS1 in the microvascular endothelium coupled to reduced serum EPAS1." (PMID 39234692, 2024). "We next sought to define the mechanism of EPAS1 reduction in obesity." (PMID 39234692, 2024). "Since microvascular EPAS1 is reduced in obesity, it will be interesting in future studies to discern whether this is linked to increased prevalence of hypertension in obese individuals." (PMID 39234692, 2024). "This study investigates the potential interplay between EPAS1, obesity, and atherosclerosis." (PMID 39234692, 2024). "We, therefore, hypothesized that suppression of EPAS1 in obesity may be related to enhanced levels of circulating TG." (PMID 39234692, 2024). "Overall, these data indicate that EPAS1 is suppressed in obese individuals associated with dyslipidemia and elevated PHD2 and PHD3 expression in EC, an observation that is consistent with our observations in murine models of obesity." (PMID 39234692, 2024). "Collectively, these observations suggest that EPAS1 reduction in obesity may result from hypertriglyceridemia-FFA metabolism coupled to localized alterations in cellular oxidative stress leading to the induction of endothelial PHD2." (PMID 39234692, 2024). "The observation that EPAS1 rescue correlated with reduced plasma TG in SFN-treated obese mice led us to hypothesize that TGs may be involved in EPAS1 suppression in obesity." (PMID 39234692, 2024). "Importantly, our findings reveal that obesity downregulates EPAS1 expression in atheroprone areas, establishing EPAS1 as a crucial intermediate link between obesity and endothelial responses to shear stress." (PMID 39234692, 2024). "We assessed whether EPAS1 suppression in obesity could be observed in blood serum and peripheral microvasculature." (PMID 39234692, 2024). "Notably, both microvascular EPAS1 and serum EPAS1 were reduced in obesity induced by HFD." (PMID 39234692, 2024). "This endothelial repair pathway is inhibited in obesity, suggesting a novel triglyceride-PHD2 modulation pathway suppressing EPAS1 expression." (PMID 39234692, 2024).
colitis (26 papers, 2015 to 2026). Inflammation of the colon. "Another study reports that overexpression of the HIF-2 PAS1 endothelial domain protein (EPAS1) led to spontaneous colitis or enhanced susceptibility to DSS-induced colitis in IEC-specific mice with Hif-2a knockouts." (PMID 36768744, 2023).
prostate carcinoma (26 papers, 2009 to 2024). A carcinoma that arises from epithelial cells of the prostate gland. "ONECUT2 activates SMAD3 and EPAS1 which mediate survival of tumor cells under hypoxic conditions as shown recently for SMAD3 in prostate cancer and in this study for EPAS1 in BPDCN." (PMID 38474011, 2024). "It was found that HIF-1α but not HIF-2α (EPAS1) depletion in BM macrophages reduced the expression of the pro-tumorigenic inflammatory cytokines Mif and Cxcl4 after being exposed to apoptotic prostate cancer cells when compared to WT BM macrophages." (PMID 36496973, 2022). "SMAD3 reportedly supports the growth of prostate cancer cells under hypoxic conditions, further supporting the notion that hypoxic adaptation may represent an important oncogenic function of ONECUT2 and its target genes SMAD3 and EPAS1 in BPDCN." (PMID 38474011, 2024).
Hepatic steatosis (25 papers, 2012 to 2025). Steatosis is a term used to denote lipid accumulation within hepatocytes. "This study poses limitations represented by that the potential involvement of Epas1 inactivation within liver PDGFRβ + cells cannot be ruled out as a factor in the control of hepatic steatosis, a caveat to the mouse models." (PMID 38509584, 2024).